PRAMEF14 (PRAME family member 14)
Synonyms: OTTHUMG00000007916
Tractability: PROTAC: ubiquitination databases record sites on it.
Gene: Protein-coding gene on chromosome 1 (13,341,892 to 13,347,134, reverse strand). Ensembl gene ENSG00000204481.
Gene Ontology:
Molecular function: ubiquitin-like ligase-substrate adaptor activity
Biological process: proteasome-mediated ubiquitin-dependent protein catabolic process; negative regulation of apoptotic process; negative regulation of cell differentiation; negative regulation of DNA-templated transcription; positive regulation of cell population proliferation
Cellular component: Cul2-RING ubiquitin ligase complex; cytoplasm
Genetic constraint (gnomAD): Loss-of-function variants: 24 observed, 33.49 expected, observed/expected ratio (o/e) 0.72, 90% interval 0.52 to 1.01. The upper end of that interval is the gene's LOEUF score, 1.01, which puts it in group 4 of 6, group 1 being the genes least tolerant of losing a copy. Missense variants: 477 observed, 525.6 expected, observed/expected ratio (o/e) 0.91, 90% interval 0.84 to 0.98. Synonymous variants: 194 observed, 204.88 expected, observed/expected ratio (o/e) 0.95, 90% interval 0.84 to 1.07.
Homologues: Orthologues: mouse Pramel12 (44% identical), rat Pramef8 (43% identical), mouse Pramel21 (41% identical), mouse Pramel11 (41% identical), mouse Pramel13 (41% identical), mouse Pramel24 (41% identical), mouse Pramel20 (41% identical), mouse Gm13040 (40% identical), mouse Gm13043 (40% identical), mouse Gm13057 (40% identical), mouse Pramel16 (40% identical), mouse Pramel4 (40% identical), and 78 more. Paralogues in human: PRAMEF1 (97% identical), PRAMEF13 (97% identical), PRAMEF2 (92% identical), PRAMEF18 (61% identical), PRAMEF19 (61% identical), PRAMEF17 (60% identical), PRAMEF10 (59% identical), PRAMEF33 (59% identical), PRAMEF12 (53% identical), PRAMEF7 (53% identical), PRAMEF8 (53% identical), PRAMEF20 (51% identical), and 12 more.